RBFOX3 (RNA binding fox-1 homolog 3)
Description:
Pre-mRNA alternative splicing regulator. Regulates alternative splicing of RBFOX2 to enhance the production of mRNA species that are targeted for nonsense-mediated decay (NMD).
Synonyms: FOX-3; NeuN; HRNBP3; FOX3
Tractability: PROTAC: ubiquitination databases record sites on it.
Gene: Protein-coding gene on chromosome 17 (79,089,345 to 79,611,258, reverse strand). Ensembl gene ENSG00000167281.
Subcellular location: Nucleus; Cytoplasm
Subcellular location (Human Protein Atlas): Nucleoplasm
Pathways (Reactome):
Gene expression (Transcription): NPAS4 regulates expression of target genes
Gene Ontology:
Molecular function: mRNA binding; nucleic acid binding; RNA binding
Biological process: nervous system development; regulation of alternative mRNA splicing, via spliceosome; regulation of RNA splicing
Cellular component: cytoplasm; nucleoplasm; nucleus
Genetic constraint (gnomAD): Loss-of-function variants: 13 observed, 34.15 expected, observed/expected ratio (o/e) 0.38, 90% interval 0.25 to 0.61. The upper end of that interval is the gene's LOEUF score, 0.61, which puts it in group 2 of 6, group 1 being the genes least tolerant of losing a copy. Missense variants: 316 observed, 374.89 expected, observed/expected ratio (o/e) 0.84, 90% interval 0.77 to 0.93. Synonymous variants: 174 observed, 157.85 expected, observed/expected ratio (o/e) 1.1, 90% interval 0.97 to 1.25.
Gene-disease validity (ClinGen):
ClinGen rates the evidence that RBFOX3 causes each of these diseases.
epilepsy (autosomal dominant): Disputed. A brain disorder characterized by episodes of abnormally increased neuronal discharge resulting in transient episodes of sensory or motor neurological dysfunction, or psychic dysfunction.
Homologues: Orthologues: chimpanzee RBFOX3 (100% identical), macaque RBFOX3 (99% identical), guinea pig RBFOX3 (98% identical), rat Rbfox3 (98% identical), mouse Rbfox3 (97% identical), dog RBFOX3 (86% identical), pig RBFOX3 (84% identical), tropical clawed frog rbfox3 (74% identical), zebrafish rbfox3a (74% identical), zebrafish rbfox3b (58% identical), Drosophila melanogaster Rbfox1 (46% identical), Caenorhabditis elegans fox-1 (34% identical). Paralogues in human: RBFOX1 (67% identical), RBFOX2 (61% identical).